APLN (apelin)
Diseases named in the same sentence as APLN in open-access papers (continued):
Sharing a sentence is not in itself a finding about the gene and the disease.
tumor (continued). "Furthermore, we examined the miR‐195 and apelin expression levels in tumor tissues using qRT‐PCR and Western blot, respectively." (PMID 31070305, 2019). "In addition, only tumors from shApln E0771 cells presented a decreased microvessel density (Fig EV2F), indicating that tumor epithelial cell‐derived Apelin induces tumor angiogenesis in a paracrine fashion." (PMID 31267692, 2019). "APLN is likely to activate tumor neoangiogenesis through paracrine-mediated action." (PMID 31410213, 2019). "Apelin has been previously shown to be upregulated in tumor cells." (PMID 31267692, 2019). "Moreover, we observed a positive correlation between apelin and apelin receptor tumour tissue level with ρ = 0.279 and p = 0.039." (PMID 31547096, 2019). "Apelin is a secreted peptide involved in regulation of tumor progression and invasiveness." (PMID 31547096, 2019). "In NeuT+ mice, Apelin ablation combined with sunitinib treatment significantly increased survival and reduced the tumor burden compared with either intervention alone; blocking Apelin almost doubled the survival of sunitinib‐treated mice and tripled the survival compared to control untreated mice." (PMID 31267692, 2019). "Pharmacological targeting of APLN robustly suppressed proliferation of HCC cells as well as the growth of tumor xenografts, implying that APLN might be a potential drug target for HCC." (PMID 31410213, 2019). "Moreover, overexpression of the apelin gene in mice resulted in tumor growth, suggesting important involvement of this adipokine in the progression of NSCLC." (PMID 31547096, 2019). "Apelin stimulation also induced expression of APJ receptor and matrix metalloproteinase-1 (MMP-1), matrix metalloproteinase-9 (MMP-9), IL-1, and IL-6, which are associated with tumor invasion and metastasis." (PMID 29875677, 2018). "Moreover, apelin plays a role in pathological angiogenesis and protects against apoptosis under tumor progression." (PMID 29875677, 2018). "Furthermore, to challenge apelin production in conditions that recapitulate the tumour microenvironment, we assessed apelin secretion from human brain endothelial cells under acidic stress." (PMID 29053791, 2017). "APLN expression was barely detectable in both normal and tumour whole tissue samples, as well as in normal and tumour epithelial cells and NECs, although a slight elevation was observed in whole tumour samples when compared to their normal counterparts." (PMID 28487489, 2017). "In keeping with a role for apelin in the stem cell maintenance, we found that differentiated GSCs were associated with a decrease in APLNR expression compared to tumourspheres and reduced tumour-initiating ability." (PMID 29053791, 2017). "Furthermore, it has been previously demonstrated that APLN promotes embryonic and tumour angiogenesis, as well as tumour growth in vivo." (PMID 28487489, 2017). "Enzyme immunoassay analysis demonstrated that endothelial cells secreted significant amounts of apelin, as the peptide was robustly detected in the conditioned media produced by human, mouse and xenograft tumour-derived endothelial cells, supporting endothelial cells as a source of apelin." (PMID 29053791, 2017). "Furthermore, the multivariate mode of COX analysis revealed that tumor Apelin expression level wasn a independent prognostic factor for the overall survival in GC patients (P = 0.003)." (PMID 27733135, 2016). "Patients with high tumor Apelin staining had a significantly shorter overall survival period compared to those with low Apelin expression and those with weak or negative Apelin staining (22.6 ± 4.9, 29.1 ± 3.7 and 30.4 ± 6.4, months, P < 0.001 by log-rank test)." (PMID 27733135, 2016). "Moreover, there is a weak positive correlation between serum Apelin concentrations and tumor Apelin expression levels." (PMID 27733135, 2016). "Apelin is expressed in cytoplasma and also in vascular endothelial cells in the tumor tissue." (PMID 27733135, 2016).
tumor (continued). "In addition, recent studies show that Apelin has lymphangiogenic potential and it is related to tumor growth and lymph node metastasis in vivo." (PMID 27733135, 2016). "Moreover, patients with high tumor Apelin level had a significantly shorter overall survival period compared to those with low Apelin expression and those with or negative Apelin staining." (PMID 27733135, 2016). "APLN+ vessels were detected in ECs of the orthotopic tumour." (PMID 25597280, 2015). "Development of potential future therapies targeting this complex pro-tumor function of the apelin/APJ pathway is thus especially intriguing as it might offer benefits to patients with malignant diseases." (PMID 24962866, 2014). "We were also interested in investigating whether transfection of tumor cells with apelin expression constructs results in an increase in tumor lymphangiogenesis in vivo." (PMID 24962866, 2014). "Resistin and apelin levels increased significantly in tumor tissues." (PMID 25049439, 2014). "We found that apelin-conjugated liposomes were specifically taken up by tumor ECs." (PMID 23799018, 2013). "Endothelial cell aggregation may be an important mechanism for apelin-mediated enlargement or maturation of blood vessels in peripheral pathological angiogenesis, including the tumor vasculature." (PMID 23640575, 2013). "Here we used apelin to assess whether tumor EC-specific drug delivery is feasible via APJ expressed on the ECs." (PMID 23799018, 2013). "In addition to the difficulty related to liposome penetration into the tumor microenvironment, fragility of apelin as a peptide also deserves consideration; it has been suggested that apelin degrades soon after intravenous injection into mice (data not shown)." (PMID 23799018, 2013). "Research implies that apelin might also participate in regulating new blood vessel growth in embryonic angiogenesis and tumor growth." (PMID 21552499, 2011). "Considering that vessel function improved upon targeting APLN, we propose that APLN+ endothelial cells may remain in an immature state and could potentially form incomplete blood vessels, thereby enabling tumor cells’ access to the circulatory system and facilitating metastasis in ESCC52." (PMID 39741182, 2025). "However, several studies have reported divergent effects of apelin on tumor progression, indicating that its impact could depend on the characteristics of the tumor microenvironment and the degree of associated immune infiltration." (PMID 41515992, 2025). "Moreover, APLN targeting could reduce tumor growth, improve blood vessels' function, reduces the invasiveness for tumor cells, and prevent resistance associated with angiogenic therapy." (PMID 38213742, 2024). "Interestingly, we observed a richer subgroup distribution of high APJ ECs in PVTT, suggesting that the apelin/APJ axis might play a role in promoting tumour hematogenous metastasis." (PMID 39434201, 2024). "In summary, depending on tumor cell types, apelin may act as a promotor of tumor proliferation." (PMID 36776217, 2023). "However, in other reports, apelin induces the growth of tumors by enhancing the tumor vasculature." (PMID 36776217, 2023). "However, several lines of evidence indicate that apelin is often over-expressed in tumors, suggesting that this factor may induce tumor growth because its expression correlates with tumor malignancy." (PMID 36776217, 2023). "This may affect complicity in the tumor growth affected by apelin." (PMID 36776217, 2023). "Since SDF1 and apelin are downregulated only in muscles from cachectic and tumor-bearing mice, it would be interesting to learn whether and how these two pathways crosstalk in muscles, like occurs for their receptors CXCR4 and APJ during blood vessel maturation." (PMID 35406586, 2022). "However, the function of apelin on tumor cells remains elusive." (PMID 36142542, 2022).
tumor (continued). "Additionally, serum apelin may be helpful in screening, whereas measures of tissue apelin are often only applicable after identifying the tumor." (PMID 36230579, 2022). "Although we found that CD8+ and CD4+ T cells accumulate more in the central areas of the tumor in the present study, whether Apelin-induced accumulation of immune cells is specific for these T cells or whether other cell types also accumulate is still not clear." (PMID 34234274, 2021). "Therefore, we selected the MC38 tumor model to analyse the function of Apelin in further studies." (PMID 34234274, 2021). "On the other hand, Apelin is also involved in the maturation of blood vessels and excessive amounts of Apelin may suppress vascular elongation of immature blood vessels in the tumor microenvironment." (PMID 34234274, 2021). "However, tumor growth in both tumor models was enhanced significantly in Apelin-KO mice." (PMID 34234274, 2021). "Therefore, to investigate whether Apelin also contributes to functional blood vessel formation in MC38 tumor models, the hypoxic status of central tumor regions was evaluated by hypoxyprobe-1." (PMID 34234274, 2021). "Thus, enhancing anti-tumor immunity might be one of the mechanisms by which Apelin is involved in tumor growth." (PMID 34234274, 2021). "Furthermore, depletion of Apelin thus enhances tumor growth, most noticeably MC38." (PMID 34234274, 2021). "Based on these results, it is possible that the real function of Apelin in tumor progression might be completely different to the current paradigm, namely that the up-regulation of Apelin in tumors may suggest a compensatory mechanism to inhibit tumor proliferation and migration." (PMID 34234274, 2021). "In addition, APLN depletion massively reduced angiogenesis-dependent tumor growth." (PMID 32545380, 2020). "Conclusively, apelin inhibition may provide a potent synergistic anti-tumor effect when combined with anti-angiogenic agents, while, and most importantly, avoiding therapy-induced hypoxia of the TME, thus decreasing the chance of metastases, and bypassing potential therapy resistances." (PMID 33469537, 2020). "Moreover, loss-of-APLN in the mouse brain further reduced GBM vessel density below normal levels that are observed in the striatum of a healthy mouse brain, underlining the switch to an avascular tumor growth." (PMID 32545380, 2020). "Therefore, we hypothesized that apelin protumoral effects might come from a modulation of the tumour microenvironment." (PMID 32681609, 2020). "Whether Apelin exerts similar effects in other tumor types requires further studies." (PMID 31267692, 2019). "Therefore, APLN overexpression could represent an interesting pharmacological target by blocking inhibition of tumor growth by increasing apoptosis and decreasing tumor vascularization." (PMID 31434359, 2019). "Also, Apelin induces the maturation of tumor blood capillaries and prompts tumor vascularization." (PMID 27733135, 2016). "We postulate that Apelin may prompt tumor invasiveness through up-regulation of these factors." (PMID 27733135, 2016). "Finally, we study whether transfection of tumor cells with apelin expression constructs results in an increase in lymphangiogenesis and LN metastasis in vivo." (PMID 24962866, 2014). "Therefore, we speculated that the apelin/APJ system could be utilized for tumor EC-specific drug delivery." (PMID 23799018, 2013). "This article reviews the currently available literature on the intracellular processes regulated by apelin/APJ, focusing on those pathways correlated with tumor development and progression." (PMID 40243599, 2025). "The strong correlations between neuropeptides PTHLH, NMB, APLN, and GAST with these neurotrophic factors suggest a coordinated mechanism through which tumor cells recruit and sustain neuronal infiltration." (PMID 40805163, 2025). "Overall, these findings demonstrate that CFE can significantly inhibit the Apelin/APJ system in HCC cells and tumor tissues." (PMID 38881868, 2024).
tumor (continued). "The utilization of inhibitors targeting apelin/APJ has led to obviously reduced metastatic foci size and enhanced tumour cell apoptosis." (PMID 39434201, 2024). "The apelin and APJ receptor systems have been suggested to regulate autophagy, apoptosis, and angiogenesis, thereby influencing tumor development." (PMID 38255203, 2024). "In our study, we localized apelin/APJ in HCC using single‐cell resolution and interpreted the spatial positioning of apelin/APJ within the tumour microenvironment (TME) through spatial transcriptomics." (PMID 39434201, 2024). "We noticed that proteins in sphingolipid signaling pathway, relaxin signaling pathway and apelin signaling pathway were up-regulated in benign lung disease when compared with both NAT and tumor groups." (PMID 38182978, 2024). "Other important proangiogenic factors and their respective cognate receptors which promotes different stages of angiogenesis in tumor are bFGF, platelet-derived growth factor (PDGF), chemokines, ephrins, angiopoietins (ANGPTs), and apelin (APLN)." (PMID 38213742, 2024). "Recently, apart from cardiovascular development, high expression of apelin and APJ has also been observed in tumor tissue compared to normal tissue, suggesting their involvement in the regulation of tumor vessel formation and normalization." (PMID 36776217, 2023). "While the VEGF/VEGFR axis is induced via autocrine mechanisms in ECs from only some patient samples (MF17, MF18, MF21), other cells in the tumor stroma secrete multiple factors that activate VEGF, BMP, PDGF, CXCR4, and apelin signaling in ECs of most samples." (PMID 37669110, 2023). "We subcutaneously inoculated B16/apelin or mock-transfected control cells into APJ-KO mice and found that B16/apelin mice showed significantly higher tumor growth than B16/mock-transfected control mice (p < 0.05)." (PMID 36776217, 2023). "Among 49 samples of human PDAC tissues, apelin and APJ were found expressed in 98% and 82% of cases, respectively, suggesting involvement of this signaling pathway in tumor growth." (PMID 36142542, 2022). "A large number of pro-angiogenic factors, including VEGF, FGF2, PDGF, angiopoietins (ANGs), ephrins (EPHs), apelin (APLN) and their related receptors and chemokines, are known to promote tumor neovascularization." (PMID 35741334, 2022). "Apelin and APJ protein expression in tumor tissues from patients with PDAC and their spatiotemporal pattern of expression in engineered mouse models of PDAC were investigated by immunohistochemistry." (PMID 36142542, 2022). "Both APLN and the Apelin receptor (APLNR) are upregulated in GBM cells and control tumor cell invasiveness." (PMID 34359800, 2021). "Taken together, these outcomes implied that APLN possessed the pro-carcinogenic effect in the KIRC xenograft model, and that the involvement of stromal cells into tumor tissue was needed for APLN to exert its effect." (PMID 35079698, 2021). "However, apelin is difficult to detect because of its low concentration in blood; thus, a potential workaround might involve transforming and amplifying the signal of apelin/Apj for tumor testing, and the cross talk between T cells and endothelial factors offers a means to implement this program." (PMID 32358530, 2020). "Several genes involved in the immune system were identified as deregulated in both studies, such as interleukins, chemokines, APLN, TNFRSF11B, TNFS9, TCF7, AZGP1, strengthening the role of tumour extracellular environment alterations in the CRC biology." (PMID 31949199, 2020). "By functional analysis of apelin in orthotopic GBM mouse models, we found that apelin/APLNR signaling is required for in vivo tumor angiogenesis." (PMID 32545380, 2020). "To better understand the roles of the top candidate genes in response to anti-VEGF inhibition, we decided to focus on APLN and APLNR, both of which were found to be upregulated in the stroma from the resistant tumors compared to sensitive tumor stroma." (PMID 32002127, 2020).
tumor (continued). "Together, these results show that autocrine signaling of endothelial apelin to APLNR-expressing vessels is required for sprouting angiogenesis to take place and shape the complex tumor neo-vasculature." (PMID 32545380, 2020). "Apelin and APJ are distributed in various tissues, including the heart, lung, liver, kidney, and gastrointestinal tract and even in tumor tissues." (PMID 33281884, 2020). "Ablation of APLN in both the GBM cells and in the tumor-bearing animals resulted in a striking cooperative anti-angiogenic effect." (PMID 32545380, 2020). "To study the role of apelin in establishing the structure and function of the GBM vascular beds and its implications to tumor growth, we here used established GBM mouse models." (PMID 32545380, 2020). "In this scenario, tumour apelin would be the main driver of TNBC progression and circulating apelin would only have an indirect effect on TNBC growth by increasing tumour apelin expression." (PMID 32681609, 2020). "In this scenario, high circulating apelin levels promote TNBC growth and the subsequent fast‐growing tumours would increase their apelin expression in order to promote angiogenesis and support their growth." (PMID 32681609, 2020). "In these hypoxic regions, APLN is co-expressed with VEGFA, suggesting a cooperative function of apelin and VEGFA in paracrine signaling from tumor to endothelial cells during GBM angiogenesis." (PMID 32545380, 2020). "In our study, we presented the correlation of apelin and APJ mRNA level between tumur, and non-tumor tissue." (PMID 31547096, 2019). "Higher expression levels of APLN and APJ were also detected in hepatocellular carcinoma tumours and in human colon adenomas and adenocarcinomas in comparison to healthy tissue." (PMID 30127323, 2018). "Apelin/APJ signaling is important for embryonic angiogenesis and is up-regulated during tumor angiogenesis." (PMID 29340118, 2017). "Upregulated neuropeptide genes, such as PTHLH, Gastrin (GAST), Secretogranin V (SCG5), Neuromedin B (NMB), and Apelin (APLN), were positively correlated with upregulated neurotrophic factors, which were consistent with their roles in tumor progression and neuroimmune crosstalk." (PMID 40805163, 2025). "Apelin may serve as a potential therapeutic target in HCC, given its role in promoting tumour angiogenesis and poor patient outcomes." (PMID 39434201, 2024). "Moreover, it was identified that CFE treatment specifically suppressed the Apelin/APJ system in HCC cells and tumor tissues." (PMID 38881868, 2024). "Furthermore, it has been observed that Apelin/APJ is highly expressed in HCC and plays a vital role in promoting arteriogenesis in the tumor." (PMID 38881868, 2024). "In this tumor model, the density of blood vessels in B16/apelin tumors did not significantly differ from that in B16/mock-transfected control tumors." (PMID 36776217, 2023). "Previously, studies indicated that the APLN–APLNR signaling nexus may become a signal to maintain the expansion and development of tumor cells." (PMID 36614283, 2023). "Taken together with our present data, more tumor cell types are likely to exist that show an aggressive migration phenotype due to a lack of apelin/APJ expression." (PMID 36776217, 2023). "APLN/APLNR signal is upregulated in several types of malignant T-cells and tumor ECs." (PMID 36959862, 2023). "Additionally, [Pyr1] apelin-13 infusion induced CD8+ T-cell infiltration into tumors, resulting in inhibition of tumor growth through C-C Motif Chemokine Ligand 8 expression." (PMID 36776217, 2023). "Conversely, levels of apelin, CCL2, progranulin, interleukin-6, chemerin, retinol binding protein 4 (RBP4), resistin, and plasminogen activator inhibitor-1 (PAI-1) expression were lower in tumor tissue than in adjacent normal tissue." (PMID 36917086, 2023).